OR4A4P (olfactory receptor family 4 subfamily A member 4 pseudogene)
Description:
Odorant receptor.
Synonyms: OR4A4
Gene: Unprocessed pseudogene on chromosome 11 (54,659,667 to 54,660,596, forward strand). Ensembl gene ENSG00000254769.
Subcellular location: Cell membrane